IL10 (interleukin 10)
Diseases named in the same sentence as IL10 in open-access papers (continued):
Sharing a sentence is not in itself a finding about the gene and the disease.
Arthritis (continued). "Repeated administration of SM-MSCs into inflamed joints could attenuate arthritis severity with reduction in inflammatory cytokines and increase in IL-10 production in serum, suggesting that local MSC treatment could exert a systemic therapeutic effect in mice." (PMID 28751919, 2017). "In this experimental paradigm, PDRN significantly improved the clinical signs of arthritis, reduced the histological damage and blunted the cartilage content and blood levels of several inflammatory cytokine, while increased the expression of the anti-inflammatory cytokine Interleukin-10 (IL-10)." (PMID 28491036, 2017). "Supporting the anti-inflammatory role of PRL in arthritis, PRL-receptor-null mice exhibited increased joint swelling and higher joint expression of the genes encoding for TNFα, IL-1β, IL-6, IFNγ, IL-17A, IL-21, IL-22, IL-23, and IL-10 when subjected to monoarticular AIA (MAIA)." (PMID 28506283, 2017). "By using an adjuvant-induced rat model of arthritis, we previously reported that the treatment with an A2AAR agonist reduced the severity of clinical signs, decreased arthritis-associated pain, and increased the serum levels of the anti-inflammatory cytokine IL-10." (PMID 28338619, 2017). "In addition, MyD88−/− mice express higher levels of the anti-inflammatory cytokine IL-10, which could also lead to reduced arthritis in the setting of elevated pathogen burdens." (PMID 24967215, 2014). "Phagocytosis of Bb by macrophages results in significant production of the anti-inflammatory cytokine IL-10, to mediate resolution of the already initiated cytokine response, a phenomenon which may play a critical role in Lyme disease severity and arthritis development." (PMID 24904837, 2014). "As the combination of TNF blockade and recombinant IL-10 had previously exhibited encouraging results in the collagen-induced arthritis model, we became interested in studying whether a combination with F8-IL10 would also exhibit a potent inhibition of disease progression." (PMID 24289726, 2013). "It is possible that the increased arthritis in the presence of anti-IFN-γ + anti IL-4 is associated with the generation of a more aggressive phenotype of Th17 cells, one that may be associated with reduced levels of IL-10." (PMID 19852819, 2009). "Finally, HSP70 did not suppress arthritis in IL-10 deficient mice, indicating that the regulatory response is IL-10 dependent." (PMID 19142233, 2009). "QRHXD and MTX significantly reduced toe swelling and arthritis, decreased inflammatory factors such as IL-1β, IL-6, IL-17, and TNF-α, and increased the anti-inflammatory factor IL-10." (PMID 40124380, 2025). "The decrease in the inflammatory Th1 and Th17 cell populations and an increase in anti-inflammatory Tregs, IL-10 and, marginally, TGF-β explains, in part, the mechanism of rFc-μTP-L309C amelioration of the arthritis in these animals." (PMID 40648884, 2025). "plant can also reduce paw and inflammatory swelling, the arthritis index, and TNF-α and IL-1β and increase the production of serum IL-10 in Freund’s complete adjuvant-induced arthritis model in rats." (PMID 38794160, 2024). "We observed that C57BL/6 APRIL-Tg mice with arthritis showed a higher percentage of T2-MZP cells, but, corroborating recent data, it is important to define this population as IL-10-producing B cells." (PMID 38691538, 2024). "Rats with FCA-induced arthritis had significantly higher levels of TNF- α, IL-10, and COX-2 (p < 0.01)." (PMID 38116080, 2023). "IL-10 restricts the polarization of M1 macrophages, blocks the IL-33/ST2 axis during arthritis, and inhibits neutrophil recruitment, matrix metalloproteinases activity, edema, and pain." (PMID 37388729, 2023). "IL-10-expressing B cells and the IL-10 density also increased in two phases during CIA, with a small increase in IL-10 in the early phase, and a profound increase in established arthritis." (PMID 36009497, 2022).
Arthritis (continued). "Studies have indicated arthritis is aggravated in CIA rats receiving anti-IL-10 antibodies, and the use of IL-10 significantly eased the collagen-induced joint swelling, infiltration, cytokine synthesis, cartilage deformity, and necrosis." (PMID 35222043, 2022). "Previous studies have shown that ellagic acid alleviated the adjuvant-induced arthritis model in mice by modulation of pro-and anti-inflammatory cytokines (IL-1β, TNF-α, IL-17, IL-10, and IFN-γ)." (PMID 35130279, 2022). "It seems T cells activated by vaccination with HSP60 peptides are mobilized to the joints affected by arthritis secreting IL‐10 and TGF‐β to finally regulate the T cell groups that potentiate adjuvant arthritis." (PMID 32808366, 2021). "Tripterygium glycosides tablets have been indicated to reduce the inflammatory response in rat lung tissue; it can upregulate IL-10 expression and TNF-α levels in the rat arthritis model." (PMID 34721642, 2021). "In corroboration, the administration of PD1 antagonist (MK0524) augments arthritis incidence and severity, increases levels of IL-1β, CXCL-1, and PGE2, whereas reduces the levels of IL-10." (PMID 34539449, 2021). "The feeding of arthritic mice with food-based Lactococcus engineered to express CFA/I fimbriae prevents arthritis by inducing CD39+ Tregs to secrete TGF-β and IL-10 and thus inhibit TNF-α production and neutrophil influx into the joints." (PMID 33442384, 2020). "Local delivery of these NPs into the joints decreased expression of STAT1, induced regression of established arthritis in the CIA model, and increased production of IL-10." (PMID 30626016, 2019). "After the induction of arthritis in mice, TNF-α and MCP-1 levels increased significantly while IL-10 levels decreased significantly in the synovial tissues of the CIA group, compared to the healthy control group." (PMID 31382595, 2019). "CKD-L, a selective HDAC6 inhibitor, decreased the arthritis score in CIA, reduced the expression of TNF and IL-1β, and increased the expression of IL-10 in PBMC from RA patients." (PMID 28673326, 2017). "IL administration of eASCs attenuated the severity and progression of arthritis, reduced bone destruction and increased the levels of regulatory T cells (CD25+Foxp3+CD4+ cells) and Tr1 cells (IL10+CD4+), in spleen and draining lymph nodes." (PMID 28484460, 2017). "The expression of miR-150, which was increased in the three models of intestinal inflammation (IL10−/−, DSS, and TLR5−/−), was unaltered in the arthritis model, as were the remaining miRNAs of the signature." (PMID 28566745, 2017). "Our data demonstrated that CKD-L, a selective HDAC6 inhibitor, decreased the arthritis score and protected against joint destruction in the CIA model, and reduced the expressions of TNF and IL-1β, and increased the expression of IL-10 in PBMC from RA patients." (PMID 28673326, 2017). "CKD-L decreased the arthritis score in CIA, reduced the expression of TNF and IL-1β, and increased the expression of IL-10 in PBMC from RA patients." (PMID 28673326, 2017). "As pro- or anti-inflammation cytokines are often related to the pathology of arthritis, we also examined the secretion levels of IL-1β, IL-6, IL-17A, TNF-α and IL-10 in AA models." (PMID 28352114, 2017). "Patients with IL-10/IL-10R defects usually present with early-onset enterocolitis and severe perianal diseases such as fissures, abscesses, or fistulas and may show other clinical features including chronic folliculitis, recurrent respiratory diseases, and arthritis." (PMID 27699073, 2016). "On the other hand, levels of both IL-10 and IFN-γ were found to be significantly elevated in both ASMA and ASTA-treated versus the untreated arthritis rats (p = 0.0000 for both antigens and both cytokines)." (PMID 27802332, 2016). "VIP contributes to the generation of Foxp3 expressing IL-10 and TGF-β producing Tregs in severe inflammatory situation like arthritis." (PMID 27022966, 2016).
Arthritis (continued). "In the CIA-induced animal model, kinsenoside improved the severity of arthritis, inhibited the progression of CIA, and increased IL-10 levels." (PMID 26916550, 2016). "Mir155-/- mice had mild arthritis similar to B6 mice, and DKO mice had severe arthritis, similar to Il10-/- mice." (PMID 26252010, 2015). "The severity of arthritis was significantly exacerbated in both C57BL/6 mice and RORγt Tg mice administrated with anti-IL-10 mAb compared with the mice with isotype control antibody, respectively." (PMID 25928901, 2015). "Ameliorative efficacy of TSE was evaluated on arthritis induced inflammation quantitatively by determining the serum levels of TNF-α, IL-1β, IL-6 and IL-10 using ELISA kits." (PMID 26059174, 2015). "Among the cytokines with the greatest importance in inflammatory responses, pain and arthritis, we selected nine cytokines for further study (IFNγ, TNFα, IL1, IL4, IL6, IL10, IL12, IL17 and IL23)." (PMID 26218592, 2015). "Among the different B-cell subsets residing in the spleens of mice with arthritis, T2-MZP B cells were found to be the main producers of IL-10 after stimulation with collagen, and the only subset that displayed a suppressive capacity both in vivo and in vitro." (PMID 26071023, 2015). "We therefore infected B6, Mir155-/-, Il10-/-, and DKO mice with B. burgdorferi for 4 weeks, after which we assessed arthritis development." (PMID 26252010, 2015). "We have used the new humanized double-transgenic model of arthritis to test oral administration of the altered peptide ligand A12 peptide and to demonstrate that T cells found in the GALT tissues release IL-10 and IL-4 in response to a murine autoantigen." (PMID 24405551, 2014). "To assess the functions of IL-10 in CIA, we used C57BL/6 IL-10−/− mice and WT mice as animal models to induce arthritis." (PMID 24742125, 2014). "In animal arthritis models, the levels of TNF-α, IL-2, and IL-10 were decreased by the HO-1 inducer cobalt protoporphyrin IX (CoPP), indicating that HO-1 deficiency causes chronic inflammatory conditions in arthritis." (PMID 25313362, 2014). "IL-10-knockout (IL-10−/−) mice and wild-type (WT) mice were immunized with chicken type II collagen (CII) to induce arthritis." (PMID 24742125, 2014). "One study reported that YJB effectively treated arthritis in rats, and our results showing that YJB affects the balance of proinflammatory cytokines IL-6/IL-10 support its anti-CIA activity, further." (PMID 22550538, 2012). "In analogy to our previous work in this area, we fused F8 to human IL10, generating the immunocytokine F8-IL10 (DEKAVIL), which was shown to preferentially localize at sites of arthritis in the collagen-induced murine model of the disease." (PMID 19781067, 2009). "Among the cytokines produced by B cells, IL-6 and IL-10 are of particular interest because of their reported production by CD5+ B cells and their respective pro- and anti-inflammatory effects in arthritis models." (PMID 19706160, 2009). "Our results demonstrate up to 125 fold increases in synovial IL1α and IL1β concentrations, approximately 30 fold increases in levels of IL6 and IL10 and a 200–300 fold elevation in synovial concentrations of TNFα during FCA-induced experimental arthritis." (PMID 17567894, 2007). "Animal studies further support the essential role of IL‐10‐producing B cells in modulating immune and inflammatory responses, as mice lacking these regulatory B cells develop severe arthritis." (PMID 41211170, 2025). "IL‐10 suppresses the production of inflammatory mediators, including IL‐1β and TNF‐α, reducing the intensity of inflammatory reactions and alleviating symptoms and inflammation in arthritis." (PMID 39554315, 2024). "Our previous randomized controlled trial and animal study found that MO could improve arthritis by decreasing pro-inflammatory factors (such as TNF-α and PGE2) and increasing anti-inflammatory factors (such as IL-10)." (PMID 38410635, 2024).
Arthritis (continued). "The cytokine/chemokine milieu suggests that disease severity in post-CHIKV arthritis is driven by processes such as IL-6-mediated inflammation and TNF-mediated T-cell chemotaxis, in addition to an immunomodulatory response from IL-10 in an attempt to regulate immune-related damage." (PMID 38507338, 2024). "The high Mg2800 diet reduced arthritis severity and joint damage and reduced synovial inflammation and the expression of cytokines while increasing the numbers of CD4+Foxp3+ Treg cells and IL10-producing Tr1 cells." (PMID 39683640, 2024). "We also planned to develop both nonspecific tolDCs using IL-10 and antigen-specific tolDCs using type II collagen for DC loading and induction of experimental arthritis." (PMID 39161770, 2024). "C57BL/6 mice lacking IL-10 exhibit more severe arthritis upon LD infection as opposed to their Bb-infected wild-type C57BL/6 controls." (PMID 37113133, 2023). "Interleukin-10 (IL-10), IL-1β, mitogen-activated protein kinase (MAPK), IL-6, matrix metalloproteinase-3 (MMP-3), TNF-α and other targets have been confirmed to play important roles in the treatment of arthritis by CC." (PMID 37637408, 2023). "Building on this work in the 2010s, the same group used chimeric mice lacking IL-10-producing B cells to show that IL-10 from B cells regulates arthritis inflammation by suppressing Th17/Th1 responses and inducing T regulatory type I cells." (PMID 36179248, 2022). "In collagen II-induced arthritis male DBA/1J mice, ginkgolide B (10, 20, and 40 μM, i.p., for 43 days) decreased the serum levels of IL-1β, IL-6, TNF-α, MMP-3, and MMP-13 and increased the anti-inflammatory cytokine IL-10." (PMID 35368757, 2022). "In addition, the CFA + MTX-GNP gel formula group registered a significant increase in serum IL-10, by 168.37%, compared to the CFA-arthritis group." (PMID 36678557, 2022). "In addition to inhibiting immunogenic CD4+ T cell populations, IL-10+ Bregs are also able to convert naïve CD4+ T cells into Tregs and IL-10-secreting type-1 regulatory CD4+ T cells (Tr1), as shown in experimental arthritis, lupus, and EAE." (PMID 33995344, 2021). "This process was dependent on IL-10 because T2-MZP B cells purified from IL-10 knockout mice failed to alleviate arthritis." (PMID 33936028, 2021). "Most importantly, treatment of WT mice with these AhR ligands in vivo demonstrated that 5-HIAA, but not KYNA, suppressed arthritis development and increased both Cyp1a1 and Il10 transcription in B cells ex vivo." (PMID 32213346, 2020). "Furthermore, in Freund's adjuvant-induced arthritis, rheumatoid markers, TNF-α, IL-10, p38 MAPK, and antioxidant parameters were measured." (PMID 31736366, 2019). "In addition, the immunologic changes of high levels of some cytokines (IL1, IL-10, TNF-α, and IL-17) and high CD4+/CD8+ T cell ratio are detected in arthritis and osteoarthritis samples." (PMID 31842790, 2019). "It was also demonstrated that mice lacking IL-1 receptor 1 on B cells have a reduced number of IL-10-producing B cells and develop exacerbated arthritis." (PMID 29895745, 2018). "In arthritis, B cells produce IL-10, which is involved in negative regulation as well as in experimental autoimmune encephalomyelitis, inflammation, and the intestinal T-dependent antigen response." (PMID 30059520, 2018). "In contrast to the induction of CD4+ Tregs by Bregs52, which is impaired in the absence of IL-10+ B cells, here, we show that the differentiation of iNKT cells that limit inflammation in arthritis is CD1d-dependent but IL-10-independent." (PMID 29449556, 2018). "Other resolutive chemokines (RANTES/CCL5, MIP2/CXCL2, MDC/CCL22), and cytokines IL-1RA and IL-10 were quantified in SuperMApo and thus added to recombinant TGF-β (all in similar quantity than measured in SuperMApo) to treat arthritis." (PMID 30542342, 2018). "On the other hand, IL-10 suppresses the production of TNF-α and progression of arthritis." (PMID 28555160, 2017).
Arthritis (continued). "The results corroborate our previous findings, using the same fusion protein approach, in the collagen-induced arthritis model showing dramatic suppressive effects on Th1 and Th17 autoaggressive CD4 T cells and upregulated regulatory T cell activities with enhanced IL10 production." (PMID 28959261, 2017). "In vivo, clinical signs of arthritis were slow down following injection of Exos but not MPs through inhibition of plasmablast differentiation and IL-10 expressing Breg cell induction." (PMID 29176667, 2017). "Transferring DCs treated with SMAs to mice can significantly reduce the severity of collagen-induced arthritis, which is accompanied by a significant generation of Foxp3+CD4+ Treg cells and/or the production of IL-10, and a reduction in IL-17+ cells in the draining lymph nodes." (PMID 29163443, 2017). "In this study, we first confirmed the therapeutic effects of MSCs on CIA mice, using generally applied quantification methods, including the paw thickness, clinical arthritis score, histological arthritis score, and modulation of proinflammatory cytokines, like IL-1β, IL-6, TNF-α, IL-10 and TGFβ1." (PMID 27354158, 2016). "A significant increase in the serum levels of IL-17 and IFN-γ was observed in the untreated arthritis group versus the normal control rats (p = 0.0000 for both cytokines), while the observed increase in IL-10 was found to be non-significant (p = 0.08)." (PMID 27802332, 2016). "IL-10 mediates the inhibitory effect of UCMSC on CDH11 expression by FLS, and this mechanism might be targeted to ameliorate arthritis." (PMID 26090476, 2015). "IL-10 mediates the inhibitory effect of UCMSC on CDH11 expression by FLS from RA patients, and this mechanism might be targeted to ameliorate arthritis." (PMID 26090476, 2015). "Likewise, the intra-articular injection of mBSA that triggers arthritis in AIA, is accompanied by a strong recall response of proinflammatory cytokines in serum, including IL-6, IL-10, IL-12, and TNF." (PMID 26512984, 2015). "The mechanism by which Breg cells influence experimental arthritis is not fully clear, although local secretion of immunosuppressive cytokines such as IL-10, or control of T-cell apoptosis remains attractive possibilities." (PMID 24945741, 2014). "Chimeric mice specifically lacking IL-10-producing B cells developed augmented arthritis, which was accompanied by a decrease of Treg cells and an increase of Th1 and Th17 cells." (PMID 24945741, 2014). "This was not sustained to 20 days and the impact of the expected MSC effect of increased IL-10 production was not sufficient to impact arthritis progression." (PMID 22812502, 2012). "Using these mice, we demonstrated that Tg mice developed more severe arthritis upon induction in the absence of IL-10 signaling." (PMID 22192790, 2011). "Choi and colleagues have shown that MSCs administered intravenously do not suppress the development of arthritis, unless they were transduced with IL-10, indicating that MSCs as such are not immunosuppressive in CIA." (PMID 20175883, 2010). "Also, co-occurrence of IL-10 and IFN-γ producing cells in synovial tissues from CT-positive arthritis patients have suggested that excessive IL-10 production suppresses IFN-γ and mediates persistence." (PMID 19397832, 2009). "HSP70 immunization of IL10−/− mice, in contrast to wild type mice (WT), did not reduce arthritis severity as compared to control, immunized IL10−/− mice." (PMID 19142233, 2009). "HSP70 vaccination did not suppress arthritis in IL-10−/− mice, indicating the crucial role of IL-10 in the protective effect." (PMID 19142233, 2009). "Lactobacillus treatment can prevent the onset of arthritis in preclinical models, reduce arthritis scores in CIA rat and pro-inflammatory cytokines (such as IL-17, IL-1β, IL-6, and TNF-α), and increase the release of anti-inflammatory cytokines like IL-4 and IL-10 in bodily fluids." (PMID 40692793, 2025).